TFPI (tissue factor pathway inhibitor)
Diseases named in the same sentence as TFPI in open-access papers (continued):
Sharing a sentence is not in itself a finding about the gene and the disease.
hemophilia (19 papers, 2016 to 2026). Hemophilia is a genetic disorder characterized by spontaneous hemorrhage or prolonged bleeding due to factor VIII or IX deficiency. "Consistent with this TFPI plasma levels correlate with bleeding risk in patients with severe haemophilia [32▪]." (PMID 39259668, 2024). "Anti-TFPI antibodies have gained attention as novel therapeutics for hemophilia, with recent FDA approvals." (PMID 41573732, 2025). "In this study, we used mathematical models to systematically analyze the impact of concizumab on TFPI’s individual anticoagulant mechanisms and, thereby, define their relative importance for restoring thrombin generation in hemophilia." (PMID 39536817, 2025). "MG1113 is a humanized immunoglobulin G4 antibody targeting the Kunitz-type protease inhibitor 2 domain of tissue factor pathway inhibitor (TFPI) and is under clinical investigation for hemophilia treatment." (PMID 41573732, 2025). "Concizumab is a monoclonal antibody that blocks FXa inhibition by TFPI and reduces bleeding in hemophilia." (PMID 39536817, 2025). "In 2024, the US FDA approved two TFPI-targeting monoclonal antibodies, concizumab and marstacimab, for the treatment of hemophilia." (PMID 41573732, 2025). "Two antibodies Concizumab, and Marstacimab that target TFPI have been in clinical evaluation for hemophilia care because of their ability to modulate blood coagulation." (PMID 38729948, 2024). "The first-in-human and proof-of-mechanism study of an anti-TFPI aptamer was conducted in hemophilia patients to test the safety and tolerability of ARC19499." (PMID 35056696, 2022). "Using an anti-TFPI aptamer (BAX 499) is a new treatment strategy for hemophilia by interfering with the TFPI inhibition of both factor Xa and the tissue factor/factor VIIa complex." (PMID 35056696, 2022). "Tissue Factor Pathway inhibitor (TFPI): It has been shown that inhibition of TFPI reduces hemophilia bleeding through activating coagulation pathways." (PMID 33692493, 2021). "Developing anti-TFPI molecules is important in treating hemophilia patients, given the limitations of factor replacement therapy." (PMID 33918821, 2021). "Regarding TFPI, recent articles investigated the biomarker as a potential treatment against haemophilia, due to its role in thrombin generation and coagulation processes." (PMID 34151535, 2021). "Moreover, it's worth noting that TFPI is currently under clinical trial for hematological malignancies like hemophilia." (PMID 38576019, 2024). "Recent advances in the development of nonfactor agents with differentmechanisms of action, such as anti-TFPI antibodies (concizumab andmarstacimab) and AT siRNA (fitusiran), hold promise for providingadditional effective treatments for patients with hemophilia withinhibitors." (PMID 39698264, 2024). "Moreover, other humanized mAbs, such as marstacimab, which specifically binds to the K1 domain of the TFPI, have shown the feasibility and efficacy of targeting TFPI therapies in hemophilia." (PMID 36569839, 2022). "In vitro and animal studies demonstrate that the inhibition of tissue factor pathway inhibitor (TFPI) could be a potential mechanism for improving coagulation in hemophilia patients." (PMID 36500686, 2022). "Together, therapeutic advances in hemophilia with targeting TFPI treatments are promising." (PMID 36569839, 2022). "The associations between PFD plasma TFPI and PPP TG endpoints resemble those reported for hemophilia, factor V deficiency, QPD, and bleeding problems of unknown cause." (PMID 34185390, 2021). "It is possible that inhibition of TFPI or its combination with human derived products such as AHF may improve the patients’ outcome by mitigating the effects of hemophilia in ARS." (PMID 33692493, 2021). "TFPI seems to have a pathologic role during hemostasis in patients with hemophilia." (PMID 27764259, 2016). "TFPI-targeted drugs CONCIZUMAB, MARSTACIMAB, ANDEXANET ALFA, and BAY-1093884 were undergoing phase I/II/III trials for hemophilia." (PMID 38576019, 2024).
hemophilia (continued). "While these results suggested that BAX499 is a candidate to treat hemophilia patients, a phase I trial evaluating ARC19499 was terminated due to the decreased TFPI clearance from aptamer binding and raising TFPI levels increased bleeding events." (PMID 33918821, 2021).
hypercoagulability (13 papers, 2012 to 2023). "Increased TF/TFPI ratio can be considered an indicator of hypercoagulable state, and has been found to be associated with increased thrombotic risk, as described in previous studies from our group." (PMID 30214417, 2018). "Thus, the possible expression alterations of TFPI due to genetic polymorphisms, might lead to a hypercoagulable state in CAD patients, which might be more essential for CAD patients complicated with diabetes." (PMID 28716011, 2017). "Indeed, in cancer patients, upregulation of TF and downregulation of TFPI were initially shown to increase the probability of developing hypercoagulability and thrombotic complications." (PMID 37238908, 2023). "EV TF/TFPI ratio and EVs pro-coagulant activity may predict a tendency to a hypercoagulable state and may be used as a marker or “red flag” in specific cases, indicating a higher risk for a thrombotic event." (PMID 28968987, 2017). "Alternatively, the insensitivity of PT and aPTT to hypercoagulation may be explained by an increase in plasma tissue factor pathway inhibitor (TFPI)." (PMID 25546432, 2014). "The EV TF/TFPI ratio might predict hypercoagulable state in β-TM patients." (PMID 30214417, 2018). "TFPI is a major inhibitor of the extrinsic coagulation pathway through its interaction with Factor Xa and tissue factor-factor VIIa complex, and heparin cofactor 2 inhibits thrombin action, thus low level of both may promote thrombophilia." (PMID 26628894, 2015).
coronary artery disease (11 papers, 2010 to 2025). "In patients with stable coronary heart disease, the T allele in the TFPI C-399T polymorphism was correlated with an increased thrombin generation in vivo, and TT homozygotes were associated with an extended ex vivo thrombin generation delay time." (PMID 34828331, 2021). "And we found that frequencies of rs7586970 and rs6434222 showed significant difference in Chinese CAD patients, indicating that the information of the TFPI gene polymorphism was helpful for evaluating the risk of developing coronary heart disease in Han Chinese." (PMID 28716011, 2017). "Genetic variations of the TFPI genes seem to be related with CAD, which likely cooperate with metabolic risk factor (diabetes mellitus) and play critical roles in the pathogenesis of coronary artery disease." (PMID 28716011, 2017). "A potential role of this protein in atherosclerotic disease has been supported by the discovery of the expression of TFPI and the reduced TF activity in carotid plaque, while increased concentrations of TFPI were detected in coronary artery disease." (PMID 36499242, 2022). "Notably, these ox-LDL-induced dynamic binding sites are enriched for the genetic risk of coronary artery disease, enabling the discovery of the gene-environment interaction of rs62172376 and ox-LDL at the CALCRL/TFPI locus." (PMID 40593292, 2025). "However, a positive correlation between plasma levels of TF and TFPI in ischemic heart disease has been demonstrated." (PMID 20444258, 2010). "Another protein detected in Hx-derived CM-EVs was the tissue factor pathway inhibitor TFPI1, which has been shown to correlate with circulating fibrinogen levels and coronary artery disease, suggesting that CM-EVs might contribute to blood coagulation under similar in vivo conditions." (PMID 30410918, 2018). "This study was designed to determine whether the variation of TFPI was related with coronary artery disease (CAD) in the Han Chinese populations." (PMID 28716011, 2017). "Finally, we established a causal patho-mechanistic network of GE and PE of IL6R, PCSK9, TFPI, and AXL and coronary artery disease providing possible new therapy targets." (PMID 35604899, 2022). "Though the study demonstrated that the T-287C variations were not correlated with an increased incidence of coronary artery disease, the results have not excluded the possibility that other gene variations in the TFPI may influence this incidence." (PMID 28716011, 2017). "This may explain occasional “paradoxical” outcomes as prolonged lag time or reduced ETP and peak height in patients in the acute phase of coronary artery disease, where counteracting forces (including TFPI) may delay but not impair thrombin generation in plasma." (PMID 23826181, 2013).
coagulopathy (10 papers, 2016 to 2024). "Research is at present also focusing on the tissue factor pathway inhibitor (TFPI), the main inhibitor of the onset of the coagulation cascade, which has been shown to regulate the severity of a wide range of hemorrhagic and coagulation disorders." (PMID 34299267, 2021). "In addition to thrombocytopenia, the dengue patients also presented coagulopathy, as demonstrated by increased D-dimer levels (p = 0.01) and TFPI plasma levels (p = 0.04) and decreased fibrinogen levels (p = 0.04) and TF plasma levels (p = 0.005)." (PMID 34578370, 2021).
endothelial dysfunction (10 papers, 2010 to 2025). In vascular diseases, endothelial dysfunction is a systemic pathological state of the endothelium (the inner lining of blood vessels) and can be broadly defined as an imbalance between vasodilating and vasoconstricting substances produced by (or acting on) the endothelium. "Increased TAFI and decreased TFPI and TM in these patients may indicate a potential hypercoagulable and hypofibrinolytic state as well as possible endothelial dysfunction, which may increase the risk of atherosclerotic and thrombotic complications." (PMID 22985614, 2012). "Mechanistically, NETs promote thrombosis by activating factor XII, degrading anticoagulants like TFPI, and enhancing endothelial dysfunction." (PMID 40076593, 2025). "The increased FL TFPI in LS patients suggests that endothelial dysfunction plays a critical role in its pathogenesis." (PMID 40376151, 2025). "By promoting endothelial dysfunction, it can influence complex regulation of the hemostatic mechanism, triggered by decreased concentrations of tissue factor pathway inhibitor (TFPl) and thrombomodulin." (PMID 34177368, 2021). "In presence of a diffuse endothelial dysfunction, the balance of the coagulation process, including the natural formation of anticoagulants, such as antithrombin, protein C and tissue factor pathway inhibitor (TFPI), is disturbed." (PMID 35054468, 2022). "Hyperglycemia may also lead to dysfunctional endothelium in which TFPI, suggested to be a marker of endothelial dysfunction, may be affected." (PMID 20444258, 2010). "Higher plasma levels of TFPI, which have been reported in CHD patients, may reflect a compensatory mechanism due to activation of the TF coagulation pathway, but may also reflect endothelial dysfunction in the atherosclerotic process." (PMID 20444258, 2010). "However, this hypothesis is supported by an increased TFPI plasmatic concentration in the case of endothelial dysfunction, a feature commonly seen after scuba diving; it was also demonstrated that dry hyperbaric exposure did not induce any change in plasmatic TFPI." (PMID 37569056, 2023).
Stroke (10 papers, 2011 to 2025). Sudden impairment of blood flow to a part of the brain due to occlusion or rupture of an artery to the brain. "The genetic associations with stroke colocalize (Posterior Probability >0.7) with the genetic associations of four proteins (TFPI, TMPRSS5, CD6, CD40)." (PMID 36253349, 2022). "The colocalization suggested the genetic variants associated with TFPI (pQTLs) were due to the same genetic variants underlying the association with any stroke." (PMID 36253349, 2022). "Notably, we found for TFPI, CD40 and CD6 that >80% of the posterior probability of colocalization of the primary genetic association with stroke and the respective protein levels were explained by a single variant (rs67492154, rs4810485 and rs2074227 for TFPI, CD40 and CD6, respectively)." (PMID 36253349, 2022). "Body mass index, white matter hyperintensity and atrial fibrillation appear to mediate the TFPI, IL6RA, TMPRSS5 associations with stroke." (PMID 36253349, 2022). "This analysis was restricted to three proteins, i.e. TFPI, TMPRSS5 and IL6RA, that showed evidence of an effect in both MRs with risk factors and stroke outcomes." (PMID 36253349, 2022). "We found the associations of TFPI, IL6RA and TMPRSS5 with stroke were likely to be mediated by one or more of these risk factors." (PMID 36253349, 2022). "TFPI 536C>T as well as THBD 127G>A was found in one stroke patient (0.7%) and one MI/PAOD patient (1.6%)." (PMID 28649568, 2017). "TFPI, CD40, IL6RA and MMP12 were associated with a lower risk of any stroke and any ischaemic stroke, while TMPRSS5 and CD6 was associated with a higher risk of any stroke." (PMID 36253349, 2022). "The association of the genetic variants selected as instrumental variables for four proteins (TFPI, TMPRSS5, CD40 and CD6) colocalized with the stroke associations (posterior probability (PP) ≥0.7) i.e. the associations in these regions were likely due to the same underlying causal variants." (PMID 36253349, 2022). "It is noteworthy to mention that miR-19a was reported to possibly modulate tissue factor pathway inhibitor (TFPI) which could signify that the up-regulation of miR-19a in cardioembolic stroke led to a pro-coagulation state in cardioembolic stroke patients." (PMID 28199366, 2017). "This prolongation may be due to release of TFPI from perturbed endothelium such as demonstrated in a recent case control study in young women with manifestations of arterial thrombosis (AMI or stroke)." (PMID 23826181, 2013). "In a study of acute ischemic stroke, 26% of stroke patients had diabetes; the authors reported significantly higher plasma numbers of TF+-MPs and an elevated circulating concentration of TF pathway inhibitor (TFPI) in stroke patients compared to healthy controls." (PMID 30915196, 2019). "As reported by others, for six proteins we observed opposite directionality of associations for plasma versus CSF protein levels (APOE, EPO, PSMP, PRSS8 and TFPI with WMHs, IL-6 with HIP-PVS, and BT3A2 with stroke)." (PMID 41266628, 2025). "We, therefore, focused further analyses on the proteins with cis-pQTLs only (i.e. TFPI, TMPRSS5, CD40, MMP12, IL6RA, CD6), as these associations with stroke are unlikely to be due to pleiotropy." (PMID 36253349, 2022). "This suggests that our TFPI D2–based MASP-2 inhibitors could be suitable for acute treatment of life-threatening disease conditions accompanied by IRI, such as myocardial infarct or stroke." (PMID 30952698, 2019).
atherosclerosis (9 papers, 2011 to 2024). A disease characterized by the build-up of fatty material and calcium deposition in the arterial wall resulting in partial or complete occlusion of the arterial lumen. "On the contrary, TFPI deficiency demonstrated a greater atherosclerotic burden in atherosclerosis-prone Apo E (−/−) mice." (PMID 28716011, 2017). "Meanwhile, heterozygous TFPI deficiency in atherosclerosis-prone mice exhibited a greater atherosclerotic burden, increased plaque tissue factor activity and decreased time to occlusive thrombosis after photochemical vascular injury." (PMID 28716011, 2017). "Furthermore, accumulating evidence of animal and clinical studies showed that TF and TFPI were closely associated with atherosclerosis and CAD." (PMID 34809656, 2021). "It is suggested that a decreased expression of ADTRP may lead to a reduction in TFPI expression and thus result in an increased risk for atherosclerosis and CAD." (PMID 28074087, 2017). "In the present study, the results showed for the first time that TFPI gene polymorphism (rs7586970 and rs6434222) could substantially influence the risk of atherosclerosis in Han Chinese." (PMID 28716011, 2017). "The deficiency of TFPI could promote atherosclerosis and thrombosis in mice highlighted a protecting role of TFPI in the pathogenesis of CAD." (PMID 25928384, 2015). "Animal studies provide supporting evidence that TFPI has a role in attenuating arterial thrombus formation and atherosclerosis development." (PMID 36253349, 2022). "This is the first study demonstrating the effect of TF and TFPI on the severity of subclinical atherosclerosis in patients living with HIV and indicating the relationship of their concentrations with antiretroviral treatment." (PMID 28749986, 2017). "Findings of our study identify TF and TFPI as potential markers for advanced subclinical atherosclerosis in HIV-infected patients and could have practical applications in primary prevention of cardiovascular diseases in people living with HIV." (PMID 28749986, 2017). "Studies on pathogenesis of atherosclerosis in the general population emphasize the role of the extrinsic pathway of blood coagulation, particularly the tissue factor (TF) and tissue factor pathway inhibitor (TFPI)." (PMID 28749986, 2017). "TFPI co-localizes with endothelial cells and macrophages in human atherosclerotic plaques, where it may modulate atherosclerosis and arterial thrombosis by attenuating TF activity." (PMID 28716011, 2017). "Consistent findings indicated a role for TFPI in the pathogenesis of atherosclerosis development, not only counteracting the role of TF but also acting as an anti-inflammatory, anti-angiogenic and lipid-lowering substance." (PMID 28716011, 2017). "This may be because of the increased severity of subclinical atherosclerosis in HIV-infected individuals, whereas the increased TFPI concentration in serum is a response to increased expression of TF by injured endothelial cells and activated monocytes." (PMID 28749986, 2017). "Excessive and/or ectopic TF-driven coagulation not adequately balanced by TFPI could lead to thrombotic complications in sepsis, atherosclerosis, lupus and cancer." (PMID 33923232, 2021).
myocardial infarction (8 papers, 2011 to 2023). Gross necrosis of the myocardium, as a result of interruption of the blood supply to the area, as in coronary thrombosis. "Decreased TFPI concentration will increase the risk of venous thromboembolism (VTE) and myocardial infarction (MI)." (PMID 32897244, 2020).
hemophilia A (7 papers, 2018 to 2025). The most common form of hemophilia characterized by spontaneous or prolonged hemorrhages due to factor VIII deficiency. "In 2024, the FDA approved two mAbs to prevent or reduce bleeding episodes related to hemophilia A and B. The first, marstacimab, which was approved on 11 October, is a human IgG1 mAb that targets tissue factor pathway inhibitor (TFPI)." (PMID 40868216, 2025). "Concizumab improved simulated thrombin generation in hemophilia A by simultaneously altering all 3 mechanisms of the TFPI anticoagulant blockade examined." (PMID 39536817, 2025). "Concizumab is a humanized monoclonal antibody against tissue factor (TF) pathway inhibitor (TFPI) that is intended for subcutaneous prophylactic treatment for persons with hemophilia A or B with or without inhibitory alloantibodies to FVIII or FIX." (PMID 39536817, 2025). "Elevated TFPI activity has been described in patients with unclassified bleeding disorders and in both hemophilia A and B. By contrast, TFPI is not a major determinant of thrombin generation in healthy individuals." (PMID 38662114, 2024). "If the currently evolving safety and efficacy data remain positive and acceptable; the anti-TFPI therapies may represent a significant advance in the care of patients with haemophilia A or B with and without inhibitors." (PMID 34026796, 2021).